STAT3 (signal transducer and activator of transcription 3)
Diseases named in the same sentence as STAT3 in open-access papers (continued):
Sharing a sentence is not in itself a finding about the gene and the disease.
necrotizing enterocolitis (2 papers, 2022 to 2024). Necrotizing enterocolitis (NEC) is a devastating disease that affects mostly the intestine of premature infants. "Furthermore, JMJD3 inhibition improved necrotizing enterocolitis (NEC) by attenuating the inflammatory response and ameliorating intestinal injury via the NF-κB and JAK2/STAT3 pathways in NEC mice." (PMID 38245781, 2024).
Neonatal sepsis (2 papers, 2024 to 2025). Systemic inflammatory response to infection in newborn babies. "This study revealed that STAT-3 is necessary for IL-27 suppression of macrophage-mediated bacterial killing, but neither myeloid-specific nor global STAT-3 inhibition during neonatal sepsis achieves the same outcome as loss of IL-27 signaling." (PMID 40130859, 2025).
obstructive sleep apnea (2 papers, 2023 to 2025). "In OSAHS (obstructive sleep apnea-hypopnea syndrome), intermittent hypoxia—a hallmark of this condition—can activate pathways including STAT3, playing a role in cellular response to hypoxic stress." (PMID 40129771, 2025). "Other targeted pathways reported for the effects of A. graveolens in neurological disorders include Nrf2 and NF-κB pathways; BDNF/ERK/mTOR (antidepressant); CNTF/CNTFRa/JAK2/STAT3 (cerebral blood flow decreases); and SIRT1/PGC-1a (obstructive sleep apnea)." (PMID 37570794, 2023). "This suggests that STAT3 and HIF1A may play significant roles in obstructive sleep apnea development with no detectable protein expressions observed for other targets in adipose tissue." (PMID 40129771, 2025).
ovarian dysfunction (2 papers, 2024 to 2026). The inability of the ovaries to function. "In KGN cells modeling LPD and POF phenotypes, cellular experiments confirmed that BaP downregulated EGFR and ESR1 expression while upregulating STAT3 expression, thereby supporting the reliability of these targets in BaP-induced ovarian dysfunction." (PMID 41828455, 2026). "In conclusion, IL-22 relies on STAT3 to directly mediate the improvement in ovarian dysfunction in PCOS in a metabolically independent manner." (PMID 38734641, 2024).
ovarian serous cystadenocarcinoma (2 papers, 2023 to 2024). A malignant serous cystic epithelial neoplasm arising from the ovary. "The top five interacting genes were selected for analysis, and the results showed that PGAP3, GRB7, STARD3, and PSMD3 had a significant positive correlations with STAT3 in TCGA cancers, such as ovarian serous cystadenocarcinoma (OV)." (PMID 36977736, 2023). "The GEPIA2 database demonstrated that the expression levels of STAT3 were different among the different breast invasive carcinoma cancer (BRCA P = 0.0359) and ovarian serous cystadenocarcinoma (OV P = 0.0213) stages." (PMID 36977736, 2023).
penile cancer (2 papers, 2022 to 2024). A primary or metastatic malignant neoplasm that affects the penis. "Much attention has been recently paid to the role of specific chemokines, which are capable of regulating STAT3 expression in penile cancer." (PMID 36230984, 2022). "During tumorigenesis phase of penile cancer, the expression evolution of JAK-STAT-SOCS1 axis was characterized by the upregulation of JAK2, STAT1, STAT2, STAT3 and STAT4." (PMID 38774752, 2024).
placental insufficiency (2 papers, 2015 to 2022). Failure of the placenta to deliver an adequate supply of nutrients and oxygen to the fetus. "NOS3 and STAT3 mRNA levels were elevated in HUAEC of patients who suffered from placental insufficiency." (PMID 25699114, 2015). "Using the HUAEC hypoxia model for placental insufficiency, we showed that Stat3 selectively bound to one of the predicted sites (namely −1.554 bp upstream of the TSS)." (PMID 25699114, 2015). "Strikingly, during simulated placental insufficiency, Stat3 turnover at the −1.554-bp binding site increased extensively." (PMID 25699114, 2015). "To further analyse the dynamic of NOS3 and STAT3 expression, we made use of an in vitro cell culture model simulating placental insufficiency by depriving HUAEC of oxygen for 24 h." (PMID 25699114, 2015).
Pneumocystis infection (2 papers, 2018 to 2019). "RT-PCR data demonstrated that IL-17 and STAT3 gene expression was significantly increased in the lung from IL-10–/– PCP mice than that from WT PCP mice at 2 wk after Pneumocystis infection." (PMID 31582901, 2019). "In our murine model of Pneumocystis infection, PCR results from lung tissue showed upregulated expressions of STAT3 and STAT5 and similar levels of STAT1 expression in IL-9−/− mice compared with WT mice." (PMID 29887863, 2018).
polyarticular JIA (2 papers, 2019 to 2021). "In the case of JIA, treatment-naive polyarticular JIA patients were found to have enhanced responsiveness to IFN-γ stimulation compared with controls (i.e., increased STAT1 and/or STAT3 phosphorylation in subsets of CD4 T cells and classical monocytes)." (PMID 33921679, 2021).
proliferative vitreoretinopathy (2 papers, 2019 to 2026). Vitreoretinal membrane shrinkage or contraction secondary to the proliferation of primarily retinal pigment epithelial cells and glial cells, particularly fibrous astrocytes, followed by membrane formation. "IL‐2 promotes cell migration, ECM synthesis and TGF‐β2 expression in RPE cells via JAK/STAT3 and NF‐κB signaling pathways, which may play an important role in proliferative vitreoretinopathy." (PMID 31608440, 2019).
psoriasis vulgaris (2 papers, 2016 to 2023). Plaque psoriasis is the most common presentation of psoriasis. "The STAT3, Tie2, and TGFβ transgene models and the imiquimod-induced model represent murine models that express some inflammatory pathways that are present in psoriasis vulgaris, but with lower fidelity in the range of pathways that are expressed in human disease." (PMID 26849645, 2016).
pulpitis (2 papers, 2020 to 2023). Inflammation of the dental pulp. "In line with our study, IL6/JAK/STAT3 signaling pathway was found to be associated with pulpitis." (PMID 36593446, 2023). "Amongst the 22 modules, the darkgray module was determined as the most pivotal module for pulpitis, from which 5 core genes, A HMOX1, LOX, ACTG1, STAT3 and GNB5, were selected, and assumed to exert pivotal effects on the pathophysiologic causal links of pulpitis." (PMID 36593446, 2023). "Subsequently, the protein coding genes HMOX1, LOX, ACTG1, STAT3, GNB5 were selected as the core genes, as they were most negatively or positively correlated modules with pulpitis statistically." (PMID 36593446, 2023). "Therefore, the role of STAT3 and GNB5 in pulpitis and material modification to regulate these two genes should be further investigated." (PMID 36593446, 2023). "However, in our study, the levels of STAT3 and GNB5 were not reversed, and these two genes were less studied in pulpitis." (PMID 36593446, 2023).
Q fever (2 papers, 2010 to 2021). A bacterial infection caused by Coxiella burnetii. "Up-regulation of the IL-10 and Stat-3 genes may account for the high susceptibility of men with Q fever to C. burnetii infection and autoantibody production." (PMID 20730052, 2010).
Respiratory tract infection (2 papers, 2019 to 2025). An infection of the upper or lower respiratory tract. "This is consistent with observations of increased susceptibility to respiratory tract infections in humans with both gain-of-function and loss-of-function Stat3 mutations." (PMID 31552035, 2019). "In summary, in the treatment of inflammation caused by respiratory tract infections, the active components of PRHT play a key role through their synergistic actions with STAT3, TNF-α, and IL-6." (PMID 40456967, 2025).
skin squamous cell carcinoma (2 papers, 2021 to 2022). A carcinoma arising from the squamous cells of the epidermis. "For example, in the squamous cell carcinoma of skin, miR-125b inhibits cell proliferation while also promoting apoptosis by targeting STAT3." (PMID 36295083, 2022). "In the squamous cell carcinoma of skin, STAT3 is regulated by miR-125b." (PMID 36295083, 2022).
Skin ulcer (2 papers, 2016 to 2023). A discontinuity of the skin exhibiting complete loss of the epidermis and often portions of the dermis and even subcutaneous fat. "STAT3 regulates the cellular stress response, as well as apoptosis and wound-healing pathways while Smad3 induces the expression of alpha-SMA, VEGF, and TGF-β1 in dermal fibroblasts and induces an increased chemotactic response, accelerating tissue repair in skin ulcers." (PMID 37269014, 2023).
spina bifida aperta (2 papers, 2021 to 2022). "We investigated the influence of signal transducer and activator of transcription-3 (STAT3) on the spinal cord tissue grafts of rat fetuses with spina bifida aperta." (PMID 34520395, 2021). "Transfection of the recombinant lentivirus-mediated STAT3 overexpression plasmid with BMSCs can help improve the efficiency of transforming into neural cells and provide new seed cells for the treatment of congenital spina bifida aperta." (PMID 34520395, 2021). "Briefly, the obtained findings provide the notion that transfection of BMSCs with a recombinant lentivirus-mediated STAT3 overexpression plasmid is able to increase the efficacy of neural cell transformation and supply fresh seed cells for treating congenital spina bifida aperta." (PMID 34520395, 2021).
squamous cell tumors (2 papers, 2015). "Thus, we hypothesize that SCC inhibition may be achieved clinically by reversing the PIAS3 deficiency present in a subgroup of squamous cell tumors, restoring its inhibition of STAT3-mediated cell proliferation." (PMID 25573684, 2015).
ST Elevation Myocardial Infarction (2 papers, 2020 to 2025). A myocardial infarction that produces elevation in the ST segments of the ECG. "FAM20A, a secreted pseudo kinase essential for biomineralization, regulates calcium-phosphate metabolism and is known to be upregulated in conditions such as ST-elevation myocardial infarction, also via the IL-6/JAK/STAT3 signaling." (PMID 40877937, 2025).
synovitis (2 papers, 2021 to 2022). Inflammation of a synovial membrane. "Extending the investigation of STAT1 and STAT3 cytokine signalling to wild‐type, Il6−/− and Il27ra−/− mice with antigen‐induced arthritis, studies show that these mice develop joint disease resembling the heterogeneous features of synovitis commonly seen in humans with rheumatoid arthritis." (PMID 34618359, 2022). "Our data agree with previous reports where phosphorylation of MAPKs and STAT-3 were increased in CIA mouse group and, positively related to the severity of synovitis, whereas dietary OLE supplementation reduced significantly both MAPKs and STAT-3 activation at transcriptional level." (PMID 33922438, 2021).
T cell deficiency (2 papers, 2017 to 2020). "T-LGL is a rare hematological condition involving T-cell receptor (TCR) rearrangement and functional T-cell deficiency, often associated with signal transducer and activator of transcription 3 (STAT3) mutation, described in 20–40% of patients with T-LGL." (PMID 29281994, 2017).
T-cell neoplasms (2 papers, 2019 to 2023). "Mutations of genes encoding for components of the JAK/STAT pathway are frequently found in T-cell neoplasms (predominantly mutations of JAK3, STAT3, and STAT5B)." (PMID 31766351, 2019).
temporal lobe epilepsy (2 papers, 2020). A localization-related (focal) form of epilepsy characterized by recurrent seizures that arise from foci within the temporal lobe, most commonly from its mesial aspect. "Together, lncRNA H19 could competitively bind let‐7b to promote hippocampal glial cell activation and epileptic seizures by targeting Stat3 in a rat model of temporal lobe epilepsy." (PMID 32648622, 2020). "LncRNA H19 could competitively bind to let‐7b to promote hippocampal glial cell activation and epileptic seizures by targeting Stat3 in a rat model of temporal lobe epilepsy." (PMID 32648622, 2020).
thyroid nodule (2 papers, 2024). A small circumscribed mass in the THYROID GLAND that can be of neoplastic growth or non-neoplastic abnormality. "Transcriptomics suggested that the (IL-6, TNF-α, IL-1β)/JAK2/STAT3/VEGF pathway may be one of the key mechanisms in the treatment of thyroid nodules by JJJG." (PMID 39494342, 2024). "Meanwhile, this study is the first to explore and suggest that the (IL-6, TNF-α, IL-1β)/JAK2/STAT3/VEGF signaling pathway may be involved in regulating the development of thyroid nodules and is one of the possible therapeutic targets for JJJG." (PMID 39494342, 2024). "Key genes involved in thyroid nodules pathogenesis and JJJG treatment were revealed, such as Il6, Il1b, Jak2, Stat3 and Vegfa, etc.." (PMID 39494342, 2024). "This study indicates that JJJG efficiently ameliorates thyroid nodules by regulating the levels of FT3, FT4 and TSH in serum and suppressing (IL-6, TNF-α, IL-1β)/JAK2/STAT3/VEGF pathway in thyroid tissue, providing a potential therapeutic approach for thyroid nodules." (PMID 39494342, 2024). "Therefore, through transcriptomics in conjunction with literatures, we speculated that JJJG may treat thyroid nodules via (IL-6, TNF-α, IL-1β)/JAK2/STAT3/VEGF pathway." (PMID 39494342, 2024).
toxoplasmosis (2 papers, 2022 to 2024). A parasitic disease contracted by the ingestion or fetal transmission of toxoplasma gondii. "The depletion of SOCS3 resulted in elevated T. gondii-induced STAT3 signaling, and macrophages and neutrophils with SOCS3 deletion had reduced levels of IL-12 and IFN-γ and succumbed to toxoplasmosis." (PMID 38297164, 2024).
vascular tumor (2 papers, 2023 to 2024). "Together, these results suggest a role of OPN stimulation of Jak/Stat3 signaling in mediating the regulation of vascular tumor cell proliferation and tumorigenicity by autophagy." (PMID 36813768, 2023). "Several lines of evidence support that autophagy-dependent expression of OPN and its autocrine stimulation of Jak/Stat3 signaling contribute to the promotion of vascular tumor cell proliferation and tumorigenicity by autophagy." (PMID 36813768, 2023). "Our data also suggested that autophagy-dependent expression of OPN and its autocrine stimulation of Jak/Stat3 signaling contribute to the promotion of vascular tumor cell proliferation and tumorigenicity by autophagy." (PMID 36813768, 2023). "Together, these results suggest that decreased Jak/Stat3 signaling downstream of OPN may contribute to the decreased tumorigenicity of vascular tumor cells." (PMID 36813768, 2023). "To further assess the role of autophagy-dependent expression of OPN and its stimulation of Jak/Stat3 signaling in vascular tumor cells, we infected Fip200 KO cells with recombinant lentiviruses encoding OPN and examined the effects of ectopic OPN expression in these autophagy-deficient cells." (PMID 36813768, 2023). "Moreover, ectopic expression of OPN rescued decreased Jak/Stat3 signaling and reversed defective proliferation and tumorigenicity of FIP200-null vascular tumor cells." (PMID 36813768, 2023). "Besides Stat3 signaling, we also observed decreased mTORC1 signaling in OPN KO tumor cells, suggesting that OPN may regulate vascular tumor cells through other signaling pathways like mTORC1." (PMID 36813768, 2023).
visceral leishmaniasis (2 papers, 2018 to 2020). A severe form of leishmaniasis characterized by irregular bouts of fever, substantial weight loss, swelling of the spleen and liver, and anemia (which may be serious). "We conclude that monocyte-like myeloid cells have increased STAT3-dependent proliferation in the spleen of hamsters with visceral leishmaniasis and that inhibition of STAT3 reduces myeloid cell proliferation and parasite burden." (PMID 33180876, 2020). "In a hamster model of visceral leishmaniasis (VL), Osorio and colleagues showed that Leishmania donovani infected macrophages displayed enhanced STAT6 and STAT3 signalling in response to the growth factors FGF2 and IGF1, further enhanced by co-stimulation with IL-4 or IL-10." (PMID 29352310, 2018).
vitamin D deficiency (2 papers, 2024 to 2025). A nutritional condition produced by a deficiency of VITAMIN D in the diet, insufficient production of vitamin D in the skin, inadequate absorption of vitamin D from the diet, or abnormal conversion of vitamin D to its bioactive metabolites. "Expression of the Chr17q21.2 genes Stat3, Stat5a, and Stat5b was not affected by vitamin D deficiency." (PMID 38567749, 2024).
Wilms tumor (2 papers, 2014 to 2016). An embryonal neoplasm characterized by the presence of epithelial, mesenchymal, and blastema components. "Synergistically overexpression of WT1 and STAT3 in tumor development, including Wilms’ tumor, increases the expression level of STAT3 target genes, including cyclin D1 and Bcl-xL, resulting in an advantage of cell proliferation." (PMID 25474318, 2014). "It is noteworthy that the locations of STAT3 and WT1 protein in primary Wilms’ tumor cells were found mostly located in the nucleus compared to prevalent cytoplasm expression in control normal cells near the tumor." (PMID 25474318, 2014).
actinopathy (1 paper, 2022). "Mechanisms underlying the allergic immune dysregulation seen in these conditions range from impaired epithelial barrier (SPINK5), to actinopathy (WAS, DOCK8), to altered antigen receptor (CARD11) and cytokine signaling (STAT3)." (PMID 35273610, 2022).
acute-on-chronic liver failure (1 paper, 2019). Acute-on-chronic liver failure (ACLF) is an extreme condition during the natural history of chronic HBV infection, with a relatively high short-term mortality. "STAT3 has been shown to be involved in the enhanced Th17 response in acute-on-chronic liver failure (ACLF) associated with HBV infection and the HBV reactivation in liver after radiotherapy." (PMID 31160486, 2019).
adrenocortical adenoma (1 paper, 2022). "As expectedly, nuclear p-S727 STAT3 positive cells were found in the adrenocortical adenoma components in Cases 1 and 3 (Case 3 > Case 1) in association with FGFR4 variant status, while no tyrosine phosphorylation of STAT3, a downstream signal of wild-type FGFR4, was found in any tumors." (PMID 35660748, 2022).
Airway obstruction (1 paper, 2025). Obstruction of conducting airways of the lung. "MUC5AC, the major glycoprotein component of mucus encoded by the conserved muc5ac gene, is expressed in airway epithelial cells and mediates IL-17A-induced mucus cell hyperplasia and mucus production via STAT3 signaling, thereby contributing to airway obstruction and inflammation." (PMID 41304567, 2025).
ameloblastoma (1 paper, 2023). The most common odontogenic tumor, arising from the epithelial component of the embryonic tooth and usually affecting the molar-ramus region of the mandible or maxilla. "It has been reported that activation of the Wnt/β-catenin pathway and IL-6/STAT3 signaling by LRP5 could promote neoplasm cells to acquire chemoresistance and the cancer stem cell phenotype, which should be considered when establishing chemotherapeutic approaches against ameloblastomas." (PMID 37628576, 2023).